BRSK2 (BR serine/threonine kinase 2)
Description:
Serine/threonine-protein kinase that plays a key role in polarization of neurons and axonogenesis, cell cycle progress and insulin secretion. Phosphorylates CDK16, CDC25C, MAPT/TAU, PAK1 and WEE1. Following phosphorylation and activation by STK11/LKB1, acts as a key regulator of polarization of cortical neurons, probably by mediating phosphorylation of microtubule-associated proteins such as MAPT/TAU at 'Thr-529' and 'Ser-579'. Also regulates neuron polarization by mediating phosphorylation of WEE1 at 'Ser-642' in postmitotic neurons, leading to down-regulate WEE1 activity in polarized neurons. Plays a role in the regulation of the mitotic cell cycle progress and the onset of mitosis. Plays a role in the regulation of insulin secretion in response to elevated glucose levels, probably via phosphorylation of CDK16 and PAK1. While BRSK2 phosphorylated at Thr-174 can inhibit insulin secretion, BRSK2 phosphorylated at Thr-260 can promote insulin secretion. Regulates reorganization of the actin cytoskeleton. May play a role in the apoptotic response triggered by endoplasmic reticulum (ER) stress.
Synonyms: C11orf7; PEN11B; SADA; STK29; SAD-A; SAD1
Tractability: Small molecule: a high-quality ligand is known; it belongs to a druggable protein family. PROTAC: UniProt records ubiquitination sites on it; ubiquitination databases record sites on it; its protein half-life has been measured; a small molecule that binds it is known.
Target class: CAMK protein kinase group; Protein Kinase; Enzyme; CAMK protein kinase BRSK subfamily; CAMK protein kinase CAMK1 family; Kinase
Gene: Protein-coding gene on chromosome 11 (1,389,899 to 1,462,689, forward strand). Ensembl gene ENSG00000174672.
Subcellular location: Cytoplasm, cytoskeleton, microtubule organizing center, centrosome; Cytoplasm, perinuclear region; Endoplasmic reticulum
Subcellular location (Human Protein Atlas): Golgi apparatus
Gene Ontology:
Molecular function: ATP binding; ATPase binding; magnesium ion binding; protein binding; protein serine/threonine kinase activity; tau-protein kinase activity; ATPase regulator activity; tau protein binding; protein kinase activity; protein serine kinase activity
Biological process: actin cytoskeleton organization; ERAD pathway; G2/M transition of mitotic cell cycle; intrinsic apoptotic signaling pathway in response to endoplasmic reticulum stress; protein phosphorylation; regulation of insulin secretion involved in cellular response to glucose stimulus; axonogenesis; establishment of cell polarity; microtubule cytoskeleton organization involved in establishment of planar polarity; neuron differentiation; regulation of axonogenesis; regulation of neuron projection development; regulation of retrograde protein transport, ER to cytosol; regulation of synaptic vesicle clustering
Cellular component: centrosome; cytoplasm; endoplasmic reticulum; distal axon; perinuclear region of cytoplasm
Genetic constraint (gnomAD): Loss-of-function variants: 17 observed, 70.73 expected, observed/expected ratio (o/e) 0.24, 90% interval 0.16 to 0.36. The synonymous counts are far from expectation, so gnomAD's model fits this gene poorly and the ratio says little. Missense variants: 793 observed, 975.03 expected, observed/expected ratio (o/e) 0.81, 90% interval 0.77 to 0.86. Synonymous variants: 515 observed, 411.35 expected, observed/expected ratio (o/e) 1.25, 90% interval 1.16 to 1.35.
Gene-disease validity (ClinGen):
ClinGen rates the evidence that BRSK2 causes each of these diseases.
complex neurodevelopmental disorder (autosomal dominant): Definitive. A disorder that involves more than one phenotype associated with the central nervous system, including but not limited to intellectual disability, autism, and seizures (epilepsy).
Homologues: Orthologues: mouse Brsk2 (98% identical), dog BRSK2 (98% identical), pig BRSK2 (97% identical), macaque BRSK2 (90% identical), rat Brsk2 (88% identical), guinea pig BRSK2 (84% identical), chimpanzee BRSK2 (82% identical), tropical clawed frog brsk2 (81% identical), zebrafish BRSK2 (81% identical), zebrafish brsk2b (80% identical), Drosophila melanogaster sff (55% identical), Caenorhabditis elegans sad-1 (52% identical), and 6 more. Paralogues in human: BRSK1 (76% identical), SIK2 (28% identical), SIK3 (27% identical), SIK1 (27% identical), MELK (24% identical), PRKAA1 (23% identical), PRKAA2 (22% identical), NUAK2 (22% identical), SNRK (22% identical), NUAK1 (21% identical), HUNK (21% identical), NIM1K (15% identical), and 5 more.